PTRH2 (peptidyl-tRNA hydrolase 2)
Description:
Peptidyl-tRNA hydrolase which releases tRNAs from the ribosome during protein synthesis. Promotes caspase-independent apoptosis by regulating the function of two transcriptional regulators, AES and TLE1.
Synonyms: PTH 2; BIT1; PTH2; CGI-147; CFAP37; IMNEPD
Tractability: Antibody: UniProt predicts a signal peptide or a membrane-spanning region. PROTAC: UniProt records ubiquitination sites on it; ubiquitination databases record sites on it; its protein half-life has been measured.
Gene: Protein-coding gene on chromosome 17 (59,674,636 to 59,707,638, reverse strand). Ensembl gene ENSG00000141378.
Subcellular location: Mitochondrion outer membrane
Subcellular location (Human Protein Atlas): Mitochondria
Pathways (Reactome):
Metabolism of proteins: Ub-specific processing proteases
Gene Ontology:
Molecular function: peptidyl-tRNA hydrolase activity; protein binding
Biological process: negative regulation of anoikis; negative regulation of gene expression; positive regulation of anoikis
Cellular component: cytosol; membrane; mitochondrial outer membrane; mitochondrion
Genetic constraint (gnomAD): Loss-of-function variants: 10 observed, 12.82 expected, observed/expected ratio (o/e) 0.78, 90% interval 0.48 to 1.32. The upper end of that interval is the gene's LOEUF score, 1.32, which puts it in group 5 of 6, group 1 being the genes least tolerant of losing a copy. Missense variants: 176 observed, 226.07 expected, observed/expected ratio (o/e) 0.78, 90% interval 0.69 to 0.88. Synonymous variants: 73 observed, 81.29 expected, observed/expected ratio (o/e) 0.9, 90% interval 0.74 to 1.09.
Homologues: Orthologues: chimpanzee PTRH2 (100% identical), macaque PTRH2 (97% identical), dog PTRH2 (88% identical), pig PTRH2 (86% identical), rabbit PTRH2 (86% identical), guinea pig PTRH2 (84% identical), mouse Ptrh2 (79% identical), rat Ptrh2 (79% identical), tropical clawed frog ptrh2 (69% identical), zebrafish ptrh2 (68% identical), Drosophila melanogaster CG1307 (42% identical), Drosophila melanogaster CG17327 (32% identical).
Diseases named in the same sentence as PTRH2 in open-access papers:
PTRH2 is named in the same sentence as 40 diseases in open-access papers, as found by Europe PMC text mining. Sharing a sentence is not in itself a finding about the gene and the disease. The quoted sentences say what the papers report.
lung carcinoma (6 papers, 2014 to 2020). "The depletion of PTRH2 protein levels in lung cancer cells (A549 and BEAS-2B) increases migration and vimentin expression but decreases E-cadherin expression thereby promoting increased metastasis in vivo." (PMID 33298880, 2020). "In lung cancer, a signaling axis containing PTRH2, ERK, and TLE1 prevents EMT." (PMID 33298880, 2020).
pancreatic disease (6 papers, 2016 to 2024). "Background/Objectives: Biallelic mutations in the PTRH2 gene are associated with a rare genetic disease known as infantile-onset multisystem neurologic, endocrine, and pancreatic disease (IMNEPD)." (PMID 39766776, 2024). "This suggests a molecular mechanism underlying the ataxia and cerebellar atrophy seen in patients with PTRH2 mutations leading to infantile-onset multisystem neurologic, endocrine, and pancreatic disease." (PMID 36219306, 2023). "PTRH2 deficiency is associated with an extremely rare disease, infantile-onset multisystem neurologic, endocrine, and pancreatic disease (IMNEPD)." (PMID 34112751, 2021). "The predominant axonal involvement seen in our patient, which was attributable to KIF1A involvement, distinguishes this syndrome from the infantile-onset multisystem neurologic, endocrine, and pancreatic disease (IMNEPD) caused by PTRH2 involvement alone." (PMID 33717719, 2021). "Infantile-onset multisystem neurologic, endocrine, and pancreatic disease (IMNEPD) has been recently linked to biallelic mutation of the peptidyl-tRNA hydrolase 2 gene PTRH2." (PMID 27129381, 2016). "According to recent reports, PTRH2 mutations have been shown to be one of the molecular mechanisms leading to ataxia and cerebellar atrophy in patients with multisystem neurological, endocrine and pancreatic diseases in infancy." (PMID 37032832, 2023). "Homozygous variants in the peptidyl-tRNA hydrolase 2 gene (PTRH2) cause infantile-onset multisystem neurologic, endocrine, and pancreatic disease." (PMID 36219306, 2023).
breast carcinoma (5 papers, 2011 to 2020). "In breast cancer, higher-grade breast carcinomas positive for lymph node metastases stain the least for PTRH2 compared to less invasive breast cancers or normal breast tissue." (PMID 33298880, 2020). "In agreement with previous findings in breast cancer, overexpression of cytosolic-PTRH2 promotes the degradation of TLE1." (PMID 33298880, 2020). "Additionally, knockdown of PTRH2 protein expression in the breast cancer cell line, MCF7 decreased anoikis sensitivity, increased cell adhesion, and decreased ERK phosphorylation." (PMID 33298880, 2020).
Ataxia (4 papers, 2020 to 2023). Ataxia refers to impaired coordination of voluntary muscle movement. "Cerebellar atrophy was reported in IMNEPD patients with the PTRH2 truncation mutation (p.Ala90fs and p.W108*) and ataxia and cerebellar hypoplasia was observed in the Ptrh2-null mice." (PMID 33298880, 2020). "This study strongly suggests that the underlying cause of ataxia and cerebellar atrophy seen in IMNEPD patients is due to the cell autonomous role that PTRH2 plays in PC maturation and survival." (PMID 36219306, 2023). "At seven days post-birth, Ptrh2-null mice are significantly smaller than age-matched littermate controls and display ataxia and muscle weakness and die within 2 weeks after birth." (PMID 33298880, 2020).
breast tumor (3 papers, 2007 to 2014). "Finally, our data revealed seven other protein coding genes (FAM33A, DHX40, CLTC, PTRH2, TMEM49, TUBD1, ABC1, and USP32) that have not been implicated previously in 17q23 studies, but whose expression was clearly associated with copy number status in primary breast tumours." (PMID 17353917, 2007).
Cerebellar atrophy (3 papers, 2020 to 2023). Cerebellar atrophy is defined as a cerebellum with initially normal structures, in a posterior fossa with normal size, which displays enlarged fissures (interfolial spaces) in comparison to the foliae secondary to loss of tissue. "We previously demonstrated cerebellar atrophy in human IMNEPD patients and Ptrh2 mutant mice as well as a strong expression of PTRH2 in murine cerebellar postmitotic PCs." (PMID 36219306, 2023).
Ductal Carcinoma In Situ (2 papers, 2011 to 2023). "Peptidyl-tRNA hydrolase 2 (PTRH2; Bit-1; Bit1) exhibits significant downregulation in advanced BC tissues compared to normal breast epithelial and ductal carcinoma in situ (DCIS) tissues." (PMID 37537585, 2023).
esophageal squamous cell carcinoma (2 papers, 2016 to 2020). Esophageal squamous cell carcinoma (ESCC) is a type of esophageal carcinoma (EC) that can affect any part of the esophagus, but is usually located in the upper or middle third. "For example, while the loss of PTRH2 expression in cancers of the lung and breast suppresses anoikis, it is upregulated in late-stage esophageal squamous cell carcinomas, perhaps because of its potent cell survival function." (PMID 33298880, 2020).
ovarian carcinoma (2 papers, 2016 to 2020). A malignant neoplasm originating from the surface ovarian epithelium. "In suspended ovarian cancer cells, estrogen (E2) binding to its estrogen (E2) binding estrogen receptor alpha (ERα) blocks the anoikis-initiating release of PTRH2 from the mitochondria and FAs to the cytoplasm through a PI3K/AKT pathway." (PMID 33298880, 2020).
esophageal cancer (1 paper, 2020). A primary or metastatic malignant neoplasm involving the esophagus. "We then discuss the role of PTRH2 and adhesion in breast, lung, and esophageal cancers focusing on signaling pathways involved in cell survival, cell growth, and cell differentiation." (PMID 33298880, 2020).
Infantile onset (1 paper, 2020). Onset of signs or symptoms of disease between 28 days to one year of life. "Interestingly, one myopathy, Infantile-onset multisystem disease with progressive muscle weakness is caused by mutations in Bit-1/PTRH-2, which controls Bcl-2 expression." (PMID 32366831, 2020).
malnutrition (1 paper, 2023). Inadequate nutrition resulting from poor diet, malabsorption, or abnormal nutrient distribution. "Since Pcp2-Cre is not widely active at P1, in order to investigate the role of Ptrh2 during early stages of PC differentiation, we went to an in vitro system to avoid the effect of malnutrition and dystrophy observed in Ptrh2−/− mice as a confounding factor." (PMID 36219306, 2023).
muscular dystrophy (1 paper, 2020). Muscular dystrophy (MD) refers to a group of more than 30 genetic diseases characterized by progressive weakness and degeneration of the skeletal muscles that control movement. "In mice, the ablation of PTRH2 alone produces a more severe and lethal myopathy similar to the muscular dystrophy phenotype found in the double knockout of dystrophin and integrin α7β161." (PMID 33298880, 2020).
neuroblastoma (1 paper, 2020). Neuroblastoma (NB) is the most common solid, extracranial childhood tumor. "We found several highly significant RBPs including RPL22L1, RNASEH2A, PTRH2, MRPL11 and AFF2, which remain uncharacterised in neuroblastoma." (PMID 32707690, 2020).
tumor (12 papers, 2007 to 2025). "Notably, PTRH2, the centrally residing gene at this locus, encodes a mitochondrial protein that induces apoptosis through interactions with the small Groucho family transcriptional regulator, AES, consistent with a tumor suppressive function." (PMID 23637631, 2013).
cancer (8 papers, 2011 to 2025). A tumor composed of atypical neoplastic, often pleomorphic cells that invade other tissues. "In the context of cancer, PTRH2 has been identified as a potential metastasis suppressor via its regulation of anoikis and EMT." (PMID 33298880, 2020). "PTRH2 regulates cell functions including cell survival and death, muscle differentiation, and cancer cell metastasis." (PMID 33298880, 2020). "In cancer, PTRH2 promotes cell survival and metastasis or cell death depending on cancer and signaling context." (PMID 33298880, 2020). "PTRH2, therefore, has great potential to be developed as a biomarker and therapeutic target for developmental disorders and specific cancers." (PMID 33298880, 2020). "It contains 10 genes with correlated expression level change, including four with prior association with cancer (NCOR1, FLCN, PEMT and PTRH2)." (PMID 24670534, 2014). "By summarizing current knowledge of PTRH2 and its essential roles in development, homeostasis, and metastasis, we hope to inspire further research of its potential as a therapeutic target in the treatment of congenital diseases and cancer." (PMID 33298880, 2020). "In contrast, in cancer PTRH2 is a potential oncogene that promotes malignancy and metastasis." (PMID 33298880, 2020). "This section will highlight the outcomes of PTRH2 signaling in specific cancers." (PMID 33298880, 2020). "However, in cancer cells with knockdown of PTRH2 protein expression, EMT is driven by active ERK inducing TLE1 repression of E-cadherin transcription." (PMID 33298880, 2020). "Due to its context-dependent effects on cell survival and cell death, the ablation of PTRH2 in different cancers may either enhance or suppress malignancy." (PMID 33298880, 2020). "Due to the heterogeneity and genetic instability of cancers, multifunctional proteins such as PTRH2 may act differently on the available pathways." (PMID 33298880, 2020). "These roles are central to PTRH2 function in IMNEPD and cancer." (PMID 33298880, 2020). "PTRH2 could affect key cellular processes involving cell reproduction and differentiation in response to adhesion by modulating the expression of Bcl2, PI3K/AKT, and ERK signaling pathways, which could promote cancer progression and metastasis." (PMID 37770477, 2023).
PTRH2 also shares sentences with these, for which no sentence is quoted: lung adenocarcinoma (4 papers); melanoma (4); metastatic disease (3); cervical cancer (2); glioma (2); non-small cell lung carcinoma (2); adenocarcinoma (1); Atrophy (1); colon carcinoma (1); colorectal cancer (1); developmental delay (1); Diabetes (1); genetic disease (1); Histiocytosis (1); Hyporeflexia (1); hypothyroidism (1); infection (1); invasive breast carcinoma (1); invasive carcinoma (1); Liver abscess (1); lung (1); myopathy (1); renal cell carcinoma (1); squamous cell carcinoma (1).